PCYT2 (phosphate cytidylyltransferase 2, ethanolamine)
Diseases named in the same sentence as PCYT2 in open-access papers (continued):
Sharing a sentence is not in itself a finding about the gene and the disease.
liver cancer (1 paper, 2025). An epithelial or non-epithelial malignant neoplasm that arises from the liver. "Therefore, we utilized in vivo and in vitro validation methods to assess the expression and mechanistic roles of PCYT2 in liver cancer cells." (PMID 40434993, 2025).
lung carcinoma (1 paper, 2022). "Recently, we developed a new PCYT2 inhibitor CHY-1 as an antitumor drug candidate to treat lung cancer." (PMID 35563655, 2022). "To validate the target, we also deleted PCYT2 in lung cancer cells LL2/LC1 using CRISPR-Cas9." (PMID 35563655, 2022). "With this new type of antitumor activity, specific inhibitors of PCYT2 and the CDP-ethanolamine Kennedy pathway offer a promising novel treatment strategy for lung cancer." (PMID 35563655, 2022).
metastatic tumor (1 paper, 2024). "Intriguingly, IHC revealed significantly lower expression of PCYT2 in live metastatic tumor compared with primary tumor, implying the possible involvement of PCYT2 in CRC liver metastasis." (PMID 39531326, 2024).
myocardial hypertrophy (1 paper, 2018). "Disruption of whole-body PE synthesis in CTP:phosphoethanolamine cytidylyltransferase (Pcyt2) +/- mice resulted in myocardial hypertrophy and cardiac dysfunction in male mice." (PMID 29320510, 2018).
papillary carcinoma (1 paper, 2022). A malignant epithelial neoplasm characterized by a papillary growth pattern. "The results revealed that metabolism-related pathways, such as oxidative phosphorylation and glycerophospholipid metabolism (PCYT2, MBOAT7, DGKA, etc.), were enriched in papillary carcinoma." (PMID 35659036, 2022).
cancer (12 papers, 2013 to 2026). A tumor composed of atypical neoplastic, often pleomorphic cells that invade other tissues. "Scd, Scd2, Dgat2, Fads2, Lpin1, Gpat3, Acaa2, Lpcat3, Pcyt2 and Pla2g4a have been reported to be closely associated with cancer." (PMID 35122680, 2022). "Initially recognized for phosphatidylethanolamine biosynthesis via PCYT2-mediated conversion, pETN gained clinical attention following reports of Brazilian cancer patients with pETN-containing products." (PMID 42110537, 2026). "Generally, PCYT2 expression is reduced in various epithelial-derived cancer cell lines compared to normal cells." (PMID 40434993, 2025). "Specifically, the downregulation of PCYT2 in cancer cells not only decreased PE level but also attenuated the interaction between PEBP1 and PPP2R1A." (PMID 39531326, 2024). "The data suggest that targeting the synthesis of PE by manipulating PCYT2 expression is a potential therapeutic approach to treat cancer." (PMID 39531326, 2024). "With these data, we can uncover the relevance of PE synthesis mechanisms affecting the Hippo signaling pathway to the pathophysiology of cancer metastasis and provide insight into PCYT2 as a potential therapeutic target for CRC." (PMID 39531326, 2024). "The synthesis of PE is catalyzed by phosphoethanolamine cytidylyltransferase 2 (PCYT2), which is ubiquitously expressed in most cells and tissues but aberrantly regulated in some cancers." (PMID 39531326, 2024). "PCYT2 was recently reported to be downregulated in cancer cells under glutamine starvation which led to accumulation of phosphoethanolamine (PEtn), and PEtn in turn enhanced the tolerance of cancer cells to starvation." (PMID 36593375, 2023). "Based on these findings, we propose that the GroP modification by PCYT2 disrupts the glycan-mediated cell adhesion to the extracellular matrix and thereby enhances cancer metastasis." (PMID 35743105, 2022). "Anticancer therapies targeting the key enzymes from the Kennedy pathway, such as CKα and PCYT2, show promise in various cancers." (PMID 35563655, 2022). "A previous study, based on metabolome analyses, demonstrated that glutamine deprivation leads to the accumulation of phosphoethanolamine (PEtn) in cancer cells through downregulation of cytidyltransferase PEtn (PCYT2)." (PMID 33809336, 2021). "Several studies imply that Pcyt2 expression is generally reduced in different epithelium derived cancer cell lineages in comparison to normal cell counterparts." (PMID 23354482, 2013). "Recently, interest in the role of PCYT2 in cancer has been growing." (PMID 40434993, 2025). "The inhibition of PCYT2 increases P-Etn levels in cancer cells and stimulates tumor growth." (PMID 40434993, 2025). "Previous studies show that PCYT2 has different roles in various cancers and cancer settings." (PMID 40434993, 2025). "Meanwhile, the IHC results show that PCYT2 was significantly overexpressed in cancer nodules." (PMID 39531326, 2024). "Furthermore, we identified a significant positive correlation between cancer progression and GroP modification, which also correlated positively with PCYT2 expression." (PMID 35743105, 2022). "PCYT2 has been also proposed as a target for novel cancer therapies." (PMID 35563655, 2022). "Thus, the present study suggests the possibility of novel approaches for cancer treatment by targeting the PCYT2-mediated GroP modification." (PMID 35743105, 2022). "Finally, the involvement of GRK4, PCYT2 and RGSL1 in cancer-related pathways and drug susceptibility needs further experimental validation." (PMID 34621245, 2021). "In addition, the nine mRNAs of the ceRNA regulatory networks included GRK4, PCYT2 and RGSL1, which showed prognostic relevance and was associated with cancer-related pathways such as DNA Damage, AR, ER, RASMAPK, and TSC-mTOR." (PMID 34621245, 2021). "Reduced expression of PCYT2 was correlated with decreased survival in cancer patients." (PMID 34829274, 2021).
cancer (continued). "As a gene that is critical for cell growth and regulation of lipid homeostasis and has been shown to be responsive to changes in the nutritional environment, Pcyt2 should be considered when developing novel approaches in the treatment of metabolic disorders and cancer." (PMID 23354482, 2013). "Regarding the mechanism whereby PCYT2 influences cancer development, a previous report showed that PCYT2 downregulation-induced phosphoethanolamine (PEtn) accumulation correlated with tumor growth under nutrient starvation, thereby PCYT2 overexpression reduced PEtn levels and tumor growth." (PMID 40434993, 2025). "Although PCYT2 regulates several human cancers, its role in HCC cells remains unknown." (PMID 40434993, 2025). "However, whether and how PCYT2 and the PE synthesis pathway influence cancer metastasis remains unclear." (PMID 39531326, 2024). "Finally, we integrate these findings into a cancer metastasis model wherein the GroP modification by PCYT2 suppresses formation of matriglycans and thereby abrogates the glycan-mediated cell adhesion to ECM, thereby promoting migration and invasion of cancer cells." (PMID 35743105, 2022). "PCYT2 could represent a target in novel metabolic strategies for cancer." (PMID 33809336, 2021). "Focusing on PCYT2 enzymatic activity, its effect on the PE synthesis pathway, and its regulation roles in tumorigenesis and metastasis will clarify the effect of phospholipid metabolism in cancer and may provide clinical opportunities for PCYT2-targeted therapy." (PMID 39531326, 2024). "Furthermore, cancer cells seem to easily adapt to starvation conditions by up-regulating Pcyt2 activity and expression which correlated with an increased cell survival and supporting the survival mechanisms could be the most critical function of Pcyt2 and PE Kennedy pathway in cancer cells." (PMID 23354482, 2013). "Based on the literature and our findings, PCYT2 in human cancers appears to have a consistent expression profile in human cancers, irrespective of tumor origin or location." (PMID 40434993, 2025). "Collectively, these findings reveal that PCYT2 inhibited the metastasis of CRC through the PCYT2/PEBP1/YAP1 axis, supporting the significance of metabolic pathways in regulation on cancer metastasis, and they shed light on PCYT2 as a potential therapeutic target for CRC metastasis." (PMID 39531326, 2024). "Given that not much is known about the PCYT2 splicing mechanism, more work is needed to fully characterize and understand the role of PCYT2 in cancer development." (PMID 35563655, 2022). "Finally, we analyzed the correlation between drug sensitivity of cancer cell lines in GDSC (Genomics of Drug Sensitivity in Cancer), and the GRK4, PCYT2 and RGSL1 expression levels." (PMID 34621245, 2021).
tumor (11 papers, 2013 to 2025). "Therefore, this novel function of PCYT2 may be associated with tumor progression, in addition to its well-established role in PE synthesis by the Kennedy pathway, which will be discussed more in the next sections." (PMID 35563655, 2022). "The results of in vivo experiments demonstrated that the tumor volume in the PCYT2 overexpression group was significantly smaller than that in the blank control group." (PMID 40434993, 2025). "We found that the fluorescence intensity of the PCYT2-overexpression group mice was weaker than that of the control group mice, indicating a decelerated growth rate of tumor cells in PCYT2-overexpression group mice." (PMID 39531326, 2024). "Although recent studies reveal the involvement of phosphatidylethanolamine (PE) synthesis enzyme phosphoethanolamine cytidylyltransferase 2 (PCYT2) in tumor chemoresistance, the effect of PCYT2 on tumor metastasis remains elusive." (PMID 39531326, 2024). "Recent studies have also revealed the involvement of PCYT2 and PE in tumor drug resistance and glutamine starvation." (PMID 39531326, 2024). "Activating transcriptional factor (ATF2) was identified as a tumor suppressor in mouse skin keratinocytes and Pcyt2 was down-regulated in the ATF2 null mice, a mouse skin carcinogenesis model." (PMID 23354482, 2013). "The results showed that the fluorescence intensity of the tumors in the LV group was weaker than that in the NC group and the tumor volume and weight in the NC group were greater than that in the LV group, suggesting that PCYT2 overexpression inhibit tumor growth in vivo." (PMID 40434993, 2025). "The pathological H&E staining also demonstrated the presence of tumor cells in the cecum, peritoneum, liver, kidney, and spleen tissues of the control group mice, while tumor cells were only observed in the cecum and peritoneum of PCYT2-overexpression group mice." (PMID 39531326, 2024). "Collectively, these results indicate that PCYT2 is critical for tumor development and metastasis and may serve as a tumor suppressor in CRC." (PMID 39531326, 2024). "Furthermore, PCYT2 overexpression reduced PEtn levels and tumor growth." (PMID 33809336, 2021). "Recent research has identified key enzymes involved in CD4+ T cell differentiation and the Kennedy pathway—ETNK1, PCYT2, and SELENOI—suggesting a potential correlation between SELENOI and tumor immunity." (PMID 39669976, 2024). "To evaluate the potential role of PCYT2, a key rate-limiting enzyme of PE synthesis pathway in CRC progression, we analyzed PCYT2 protein expression difference between tumor and normal tissue in the publicly available datasets." (PMID 39531326, 2024). "In the current study, we showed that PCYT2 expression was downregulated in tumor tissues compared with adjacent tissues, and patients with CRC had a better prognosis when they showed higher PCYT2 expression." (PMID 39531326, 2024). "We also found that tumor infiltration of CD3+ T and CD8+ T cells, CCR5 expression, and T-cell activation in tumors were all significantly reduced after PCYT2 knockdown." (PMID 39872623, 2023). "In addition, GRK4, PCYT2 and RGSL1A are potential TGCT-specific biomarkers that can predict RFS, tumor immunity and chemotherapeutic resistance." (PMID 34621245, 2021). "To further assess whether PE participated in Arf1 ablation-­induced tumor suppression or not, we generated tumor cells with CTP:phosphoethanolamine cytidylyltransferase (PCYT2) knockdown, which catalyzes the synthesis of PE from ethanolamine." (PMID 39872623, 2023).
metabolic disease (4 papers, 2013 to 2025). A congenital disorder (due to inherited enzyme abnormality) or acquired (due to failure of a metabolically important organ) disorder resulting from an abnormal metabolic process. "Another study showed that Pcyt2 mRNA was reduced in a mouse model of Wilsone disease, a severe metabolic disorder characterized by significant liver damage caused by genetic inactivation of copper-transporter, ATP7B." (PMID 23354482, 2013). "Together this suggests the candidacy of PCYT2 gene and importance of establishing the significance of reduced PCYT2 activity in metabolic diseases." (PMID 35058529, 2022). "We have previously shown that Pcyt2 + /- mice exhibit changes in liver metabolic regulators from young age but do not clinically manifest metabolic disease and NASH until adulthood." (PMID 40153413, 2025).
neurological disorders (3 papers, 2013 to 2025). "Mutations in DYNC1H1 gene have been associated with neurological diseases in humans and here we show Pcyt2 + /- mice exhibit decreased methylation and expression." (PMID 40153413, 2025). "Indeed, loss of function of both PCYT2 and PLA2G6 leads to severe neurological disorders, with biallelic mutations in PCYT2 causing a complex form of HSP with optic nerve atrophy, which is associated with neutral ether lipid and ether phospholipid abnormalities." (PMID 37463447, 2023).
infection (2 papers, 2024 to 2025). The state of being infected such as from the introduction of a foreign agent such as serum, vaccine, antigenic substance or organism. "Does the inhibition of PCYT2 enzymatic activity affect the infection of CRFK cells by FPV013?" (PMID 40919194, 2025). "PCYT2, a phospholipid synthesis enzyme which positively regulates formation of lipid droplets increased EBOV infection in Huh7 cells, while decreasing infection in HeLa cells." (PMID 38617272, 2024).
PCYT2 also shares sentences with these, for which no sentence is quoted: Ataxia (2 papers); asthma (1); atherosclerosis (1); colorectal cancer (1); complement deficiency (1); End Stage Liver Disease (1); Hyperglycemia (1); hyperuricemia (1); hypoalphalipoproteinemia (1); Insulin-resistant Diabetes (1); kidney stone (1); lipoprotein deficiency (1); liver (1); liver fibrosis (1); Polydipsia (1); rhabdomyosarcoma (1); type 2 diabetes (1).